GDNF (glial cell derived neurotrophic factor)
Diseases named in the same sentence as GDNF in open-access papers (continued):
Sharing a sentence is not in itself a finding about the gene and the disease.
Cerebral ischemia (29 papers, 2009 to 2025). Restriction of arterial blood supply to the brain associated with insufficient oxygenation to support the metabolic requirements of the tissue. "In contrary, we found cerebral ischemia exerts dual opposite effects on the expression of GDNF in the striatum and cortex." (PMID 35879657, 2022). "In cultured hippocampal neurons, brain ischemia downregulates the neuroprotective GDNF-Ret signaling by a calpain-dependent mechanism." (PMID 31456664, 2019). "Experimental and clinical studies have shown that BDNF and GDNF are upregulated at very early stages during brain ischemia." (PMID 26706245, 2016). "In this work, we show that the Ret51 protein is selectively downregulated following excitotoxic injury and in brain ischemia, by a calpain-dependent mechanism, with a consequent decrease in GDNF signaling activity." (PMID 25675305, 2015). "The glial line-derived neurotrophic factor (GDNF) is a potent neurotrophic factor and an established neuroprotector in various models of cerebral ischemia and has been long identified as another attractive pharmacological target." (PMID 27713257, 2010). "Furthermore, there is evidence suggesting that GDNF derived from RAs promotes neuronal survival and facilitates brain repair and recovery, ultimately leading to improved long-term outcomes following cerebral ischemia." (PMID 39596535, 2024). "During cerebral ischemia, GDNF can reduce infarct size by preventing neuronal apoptosis." (PMID 36338029, 2022). "In this study, T3 was intra-ventricularly injected to evaluate gene expression and protein concentration of and brain-derived neurotrophic factor (BDNF) and Glial cell-derived neurotrophic factor (GDNF) in hippocampal CA1 region in rat model of brain ischemia/reperfusion (I/R)." (PMID 28202057, 2017). "Numerous studies have revealed that glial cell-derived neurotrophic factor (GDNF) exerts neuroprotective functions during cerebral ischemia and neurotoxicity; thus, GDNF may hold a pivotal position in the interaction between MG and neurons." (PMID 28018176, 2016). "Transient brain ischemia alters the expression of the GDNF signaling machinery but whether the GDNF receptor proteins are also affected, and the functional consequences, have not been investigated." (PMID 25675305, 2015). "The downregulation of Ret51 after excitotoxic injury in cultured hippocampal neurons and in brain ischemia may affect the neuroprotective signaling induced by GDNF." (PMID 25675305, 2015). "Because of the potential protective properties of GDNF in several neurodegenerative disorders such as cerebral ischemia/hypoxia and spinal cord injury, GDNF is of special interest for the development of a neurotrophic factor-based therapy for the treatment of neurodegenerative disorders in humans." (PMID 26317008, 2014). "We previously demonstrated that intracerebral infusion of GDNF protects against cerebral ischemia." (PMID 19534760, 2009). "DMF is capable of providing neurotrophic factors, such as BDNF, GDNF, and NT3, these neurotrophic molecules being directly related to axonal elongation after peripheral nerve injury and during development and also having been associated with motor recovery after cerebral ischemia." (PMID 37571065, 2023). "BM-MSCs can increase astrocyte proliferation and activate astrocytes through the production of GDNF (detected in the present study in the transplanted BM-MSCs), which could together contribute to a functional improvement in brain ischemia present in hydrocephalus with high ICP." (PMID 36982724, 2023). "Interestingly PEA was shown to increase hippocampal neurogenesis and neuroplasticity in an established murine model of autism, and prevented the decrease in brain-derived neurotrophic factor (BDNF) and glial cell line-derived neurotrophic factor (GDNF) in a murine model of cerebral ischemia." (PMID 34069940, 2021).
Cerebral ischemia (continued). "To assess the impact of brain ischemia on the expression of AQP4 and GDNF in EV cargo, we analyzed these proteins’ band intensities in the TEVs and ADEVs of AIS patients (D1, D7: n = 18, M1: n = 12) and compared them to those of the control subjects (n = 9)." (PMID 39596535, 2024). "In the striatum, relative expression of GDNF and VEGF remarkably down-regulated following cerebral ischemia; while expression of NT-3 and BDNF was increased more than 600 and 200%, respectively." (PMID 35879657, 2022). "BMSCs overexpressing glial cell-derived neurotrophic factor (GDNF) and placental growth factor (PlGF) display better neuroprotective effects in the rodent model of ICH and cerebral ischemia." (PMID 35769327, 2022). "In the present study, with regard to BDNF and GDNF, cerebral ischemia increased its protein expression levels, which is consistent with a previous study that reported elevated BDNF and GDNF protein expression in transient cerebral ischemia." (PMID 30046341, 2018). "The therapeutic potentials of NCM, TGFβ1, GDNF, NT-3 and DADS in the control of cerebral ischemia in human therefore have been suggested and require further investigation." (PMID 26745377, 2016). "The contribution or involvement of TGFβ1, GDNF, NT-3, ERK or Akt in NCM-mediated brain protection against cerebral ischemia however, remained still unclear." (PMID 26745377, 2016). "To date, the efficacy of PTD fusion proteins, including the anti-apoptotic protein Bcl-xL, neurotrophic factor GDNF, and antioxidant enzyme SOD, have been demonstrated in rodent models of cerebral ischemia." (PMID 23094105, 2012). "Previous reports demonstrated that transplantation of gene-modified human MSCs overepressing GDNF, BDNF, or VEGF after cerebral ischemia reduce infarct volume and ameliorate neurological deficits." (PMID 20668522, 2010). "Some experiments found that exogenous T3 and T4 elevated the concentrations of certain important neuroprotective agents, such as brain-derived neurotrophic factor (BDNF) and glial cell-derived neurotrophic factor (GDNF), in a rat model of brain ischemia/reperfusion." (PMID 29176727, 2017). "Likewise, it was shown that Hpc-bone marrow MSCs (BM-MSCs) enhanced the angiogenesis and neurogenesis in cerebral ischemia rat model through upregulation of growth factors including BDNF, GDNF, VEGF, and erythropoietin with downregulation of inflammatory cytokines." (PMID 33381188, 2020).
ischemia (28 papers, 2009 to 2025). A hypoperfusion of the BLOOD through an organ or tissue caused by a PATHOLOGIC CONSTRICTION or obstruction of its BLOOD VESSELS, or an absence of BLOOD CIRCULATION. "The current study found that administering Prdpn had a neuroprotective impact and improved functional recovery in ischemia-reperfusion models of spinal cord injury by increasing GDNF and BDNF spinal expression levels." (PMID 39937253, 2025). "It was also revealed that both surviving neurons and ischemia-induced astrocytes produce GDNF between the third and seventh day following the onset of ischemia." (PMID 39596535, 2024). "Another interesting study reported that ischemia-injured neurons were rescued by astrocytic GDNF modulation suggesting a wider role for GDNF in preserving and promoting brain health and recovery." (PMID 37237908, 2023). "Delivery of the GDNF gene reduced the death of neurons in the cerebral cortex in ischemia by preventing apoptotic processes activation." (PMID 36077134, 2022). "In this context, GDNF and dopaminergic neurons perfectly match puzzle pieces to enlighten ischemia pathophysiology and open ways for regenerative treatments." (PMID 34773698, 2022). "The highest GDNF immunoreactivity in astrocytes is observed between the 3rd and 7th day from the ischemia onset." (PMID 31701356, 2020). "By promoting cell survival, neurite outgrowth, and synaptogenesis, GDNF alleviates the ischemia-induced learning and memory disorders." (PMID 31701356, 2020). "In ischemia/reperfusion rats, Wharton’s jelly-derived mesenchymal stem cells obviously increased gene expression of GDNF and BDNF and improved the functional learning and memory." (PMID 32265642, 2020). "Glial derived neurotrophic factor (GDNF) is well known factor to rescue neurons following ischemia, neurodegeneration or neurotrauma." (PMID 29180963, 2017). "For instance, intrastriatal injection of glial cell line-derived neurotrophic factor (GDNF) has been seen to induce neurogenesis after ischemia." (PMID 28698874, 2017). "Tat was moreover conjugated to the 9-amino acid C-terminal part of the N-methyl-d-aspartate receptor (NMDA) NR2B subunit (NR2B9c) and the glial-derived neurotrophic factor (GDNF) for delivery into the brain to prevent ischemia." (PMID 26840305, 2016). "OGD, which is a common method to construct in vitro models for ischemia research, leads to forms of injury including neuronal necrosis and apoptosis, whereas GDNF exerts a protective effect on neurons, stimulating viability, proliferation and survival." (PMID 28018176, 2016). "This loss of Ret51 receptors impairs the neuroprotective effects of GDNF after transient in vitro ischemia." (PMID 25675305, 2015). "In this context, studies have shown that ischemia-induced glial cell activation results in the release of glial cell line-derived neurotrophic factor (GDNF), which increases glutamate uptake, thereby potentially facilitating neuroprotection by reducing glutamate-induced excitotoxicity." (PMID 33796062, 2021). "In addition to BDNF, GDNF was found to protect neuronal damage against ischemia, drug abuse, and pain." (PMID 23304227, 2012). "The present observation of increased GDNF striatal levels following DADLE treatment suggests that the striatal dopaminergic system is a highly potent target for DADLE in reversing ischemia cell injury, as well as other diseases characterized by dopamine dysfunctions." (PMID 19534760, 2009). "In in vitro models of ischemia, high-frequency repetitive magnetic stimulation (HF-rMS) was shown to have a direct modulatory effect on astrocytes and stimulate the release of trophic factors, including GDNF and PDGF-BB from their secretome, which promoted neuronal survival after ischemic period." (PMID 39062133, 2024). "In addition, DEX-induced activated astrocytes may promote the release of glial cell line-derived neurotrophic factor (GDNF) to rescue neurons after ischemia injury." (PMID 31654225, 2020).
ischemia (continued). "Borlongan and colleagues have shown that 3 days after intravenous administration of human umbilical cord-blood cells, there was an increased expression of BDNF, GDNF, and NGF in the rat brain after ischemia, compared to control animals." (PMID 26607630, 2016). "The most commonly evaluated trophic factors in experimental models of ischemia include BDNF, GDNF, EGF, FGF-2, VEGF, and IGF-1." (PMID 26607630, 2016). "Delivery of the HSVgdnf amplicon 3-days post MCOA, however, did not serve to protect neurons from ischemia-induced death, thus highlighting GDNF’s neuroprotective role rather than neurorestorative activity in the setting of modeled ischemia." (PMID 19956558, 2009). "Reactive astrocytes express various neurovascular trophic factors and chemokines such as SDF-1α, VEGF, glial cell derived neurotrophic factor (GDNF), and brain-derived neurotrophic factor (BDNF), which may positively contribute to neurogenesis, angiogenesis and neurite outgrowth following ischemia." (PMID 30524673, 2018).
neuroblastoma (21 papers, 2007 to 2025). Neuroblastoma (NB) is the most common solid, extracranial childhood tumor. "Although GDNF is frequently described as oncogenic in various cancers, including EC, some studies suggest it may also regulate neuronal differentiation at post-migratory stages and has been implicated in the regulation of growth, differentiation, and apoptosis in neuroblastomas." (PMID 41262902, 2025). "We can even state that Pro-mGDNF (GDNF with the deleted Prе-region) showed more significant results as a factor supporting the viability of SH-SY5Y neuroblastoma cells." (PMID 34634077, 2021). "In a human neuroblastoma cell line, the administration of its receptor ligand GDNF compensates morphological and bioenergetic deficits of PINK1-deficient cells without affecting mitophagy." (PMID 28768533, 2017). "This is in contrast with previous reports that demonstrate that GDNF can increase dopamine levels via the regulation of TH gene expression in a Ret-dependent response in human neuroblastoma cell lines and in grafts of human ESC-derived DaNs into an environment of GDNF overexpression." (PMID 34239871, 2021). "Dok4 was shown to regulate GDNF/Ret dependent neurite outgrowth in neuroblastoma cells." (PMID 18021428, 2007). "The literature investigating GDNF-RET signalling predominantly originates from experiments in cancer cell lines, such as SH-SY5Y neuroblastoma lines, which express RET at high levels following retinoic acid differentiation." (PMID 35798698, 2022). "9cRA enhances production of glial cell line derived neurotrophic factor (GDNF), and bone morphogenetic protein-7 (BMP-7) protein, in human neuroblastoma cells and U2 OS cells, respectively." (PMID 23040108, 2012). "NF-κB also regulates the expression of glial cell-derived neurotrophic factor (GDNF) family receptor α1, which influences the responsiveness of Neuro2a neuroblastoma cells to GDNF." (PMID 21459462, 2011). "Moreover, GDNF modulates the rate of neuroblastoma (NB) and glioblastoma cancer cell proliferation." (PMID 28878618, 2017). "Upon addition of glial cell line-derived neurotrophic factor (GDNF), a growth factor and ligand for RET that neuroblastoma cells secrete, cell proliferation was stimulated in non-adherent neuroblastoma cells but not in adherent cells." (PMID 26771642, 2016).
Anxiety (20 papers, 2013 to 2025). Intense feelings of nervousness, tension, or panic often arise in response to interpersonal stresses. "In contrast, GDNF-releasing hiAd-MSCs only reduced epilepsy-associated anxiety levels at 5 weeks after transplantation." (PMID 40839114, 2025). "According to these results association of rs3812047 and rs3096140 GDNF polymorphisms with anxiety was consistent across participant subgroups." (PMID 24324616, 2013). "Previous research has established the role of GDNF in various mental disorders, including mood disorders, anxiety, and bipolar disorder." (PMID 39881227, 2025). "Instead, animal models which cannot up-regulate GDNF during stress exhibit anxiety, anhedonia and disrupted LI." (PMID 38601326, 2024). "For example, a CpG site in the glial cell-derived neurotrophic factor (GDNF) gene showed higher DNA methylation compared to low or moderate pregnancy-related anxiety." (PMID 30925934, 2019). "In the nucleus accumbens (NAc), glial cell-derived neurotrophic factor (GDNF) expression appears to be reduced in chronic early life stressed mice with anxiety- and depressive-like behaviors." (PMID 30984237, 2019). "Addicted rats displayed increased anxiety, which was improved by GDNF treatment (p < 0.05)." (PMID 40371361, 2025). "In a similar study, GDNF delivery to the hippocampus via encapsulated GDNF-release cells resulted in decreased anxiety and alleviated seizure frequency, indicating that GDNF therapies may also address the neuropsychiatric comorbidities of epilepsy." (PMID 33815100, 2021). "Both GDNF SNPs explained 0.8% of the variability of anxiety." (PMID 24324616, 2013). "In light of results presented here, GDNF might be one of the common factors that links anxiety to substance abuse." (PMID 24324616, 2013). "This is the first report on association between anxiety and the polymorphisms of GDNF gene; however, since we used a non-clinical sample we could assess genetic background of individual variation in anxiety below the clinical threshold." (PMID 24324616, 2013). "In conclusion, this is the first demonstration of a significant association between the GDNF gene and mood characteristics demonstrated by the association of two SNPs of the GDNF gene (rs3812047 and rs3096140) and individual variability of anxiety using self-report data from a non-clinical sample." (PMID 24324616, 2013). "Behavioral differences were also noted: Ctrl-MSCs improved short-term memory and reduced anxiety, whereas GDNF-MSCs primarily reduced anxiety without significantly improving memory." (PMID 40839114, 2025). "This sorting route provides an efficient pathway for clearance of GDNF from the extracellular space and counteracts consequences of excessive GDNF signaling, such as hyperactivity and reduced anxiety (as seen in mice lacking SORLA)." (PMID 27832290, 2017).